LGR4 (leucine rich repeat containing G protein-coupled receptor 4)
Description:
Receptor for R-spondins that potentiates the canonical Wnt signaling pathway and is involved in the formation of various organs. Upon binding to R-spondins (RSPO1, RSPO2, RSPO3 or RSPO4), associates with phosphorylated LRP6 and frizzled receptors that are activated by extracellular Wnt receptors, triggering the canonical Wnt signaling pathway to increase expression of target genes. In contrast to classical G protein-coupled receptors, does not activate heterotrimeric G proteins to transduce the signal. Its function as activator of the Wnt signaling pathway is required for the development of various organs, including liver, kidney, intestine, bone, reproductive tract and eye. May also act as a receptor for norrin (NDP), such results however require additional confirmation in vivo. Required during spermatogenesis to activate the Wnt signaling pathway in peritubular myoid cells. Required for the maintenance of intestinal stem cells and Paneth cell differentiation in postnatal intestinal crypts. Acts as a regulator of bone formation and remodeling. Involved in kidney development; required for maintaining the ureteric bud in an undifferentiated state. Involved in the development of the anterior segment of the eye. Required during erythropoiesis. Also acts as a negative regulator of innate immunity by inhibiting TLR2/TLR4 associated pattern-recognition and pro-inflammatory cytokine production. Plays an important role in regulating the circadian rhythms of plasma lipids, partially through regulating the rhythmic expression of MTTP (By similarity). Required for proper development of GnRH neurons (gonadotropin-releasing hormone expressing neurons) that control the release of reproductive hormones from the pituitary gland (By similarity).
Synonyms: GPR48; BNMD17; DPSL
Tractability: Small molecule: a structure with a bound ligand is known; it belongs to a druggable protein family. Antibody: a drug acting on it is in phase 2 or 3 trials; UniProt places it where antibodies can reach, with high confidence; its Gene Ontology location is reachable by antibodies, with high confidence; UniProt predicts a signal peptide or a membrane-spanning region. PROTAC: ubiquitination databases record sites on it.
Gene: Protein-coding gene on chromosome 11 (27,365,961 to 27,472,821, reverse strand). Ensembl gene ENSG00000205213.
Subcellular location: Cell membrane
Subcellular location (Human Protein Atlas): Centrosome; Basal body; Centriolar satellite
Pathways (Reactome):
Signal Transduction: Regulation of FZD by ubiquitination
Gene Ontology:
Molecular function: G protein-coupled receptor activity; protein binding; transmembrane signaling receptor activity; protein-hormone receptor activity
Biological process: positive regulation of canonical Wnt signaling pathway; bone mineralization; bone remodeling; circadian regulation of gene expression; negative regulation of cold-induced thermogenesis; negative regulation of cytokine production; negative regulation of toll-like receptor signaling pathway; osteoblast differentiation; spermatogenesis; circadian rhythm; G protein-coupled receptor signaling pathway; metanephric glomerulus development; metanephric nephron tubule morphogenesis; positive regulation of branching involved in ureteric bud morphogenesis; positive regulation of Wnt signaling pathway
Cellular component: plasma membrane; membrane
Genetic constraint (gnomAD): Loss-of-function variants: 18 observed, 36.78 expected, observed/expected ratio (o/e) 0.49, 90% interval 0.34 to 0.73. The upper end of that interval is the gene's LOEUF score, 0.73, which puts it in group 2 of 6, group 1 being the genes least tolerant of losing a copy. Missense variants: 670 observed, 711.76 expected, observed/expected ratio (o/e) 0.94, 90% interval 0.88 to 1. Synonymous variants: 291 observed, 290.3 expected, observed/expected ratio (o/e) 1, 90% interval 0.91 to 1.11.
Homologues: Orthologues: chimpanzee LGR4 (99% identical), macaque LGR4 (99% identical), rabbit LGR4 (97% identical), pig LGR4 (94% identical), rat Lgr4 (93% identical), mouse Lgr4 (93% identical), dog LGR4 (88% identical), tropical clawed frog lgr4 (74% identical), zebrafish lgr4 (60% identical), Drosophila melanogaster kek3 (15% identical), Caenorhabditis elegans sma-10 (15% identical), Drosophila melanogaster Con (13% identical), and 1 more. Paralogues in human: LGR6 (45% identical), LGR5 (45% identical), LRIG1 (20% identical), LRIG2 (19% identical), LRIG3 (19% identical), TRIL (13% identical), CHADL (13% identical), CPN2 (13% identical), LRRTM2 (12% identical), LRIT3 (11% identical), LRRC24 (10% identical), LGI1 (10% identical), and 10 more.
Diseases named in the same sentence as LGR4 in open-access papers:
LGR4 is named in the same sentence as 111 diseases in open-access papers, as found by Europe PMC text mining. Sharing a sentence is not in itself a finding about the gene and the disease. The quoted sentences say what the papers report.
Obesity (14 papers, 2015 to 2025). Accumulation of substantial excess body fat. "Deficiency of hypothalamic LGR4 rendered mice resistant to diet-induced-obesity via increasing energy expenditure and reducing food intake." (PMID 40069508, 2025). "Collectively, these results demonstrate that deficiency of LGR4 in neurons protects against diet-induced obesity by decreasing food intake and increasing energy expenditure through improved leptin sensitivity." (PMID 40069508, 2025). "In humans and mice, Lgr4 mutations and expression levels have been directly associated with obesity and type-2 diabetes traits." (PMID 39033139, 2024). "LGR4 in particular has been implicated in obesity-related metabolic dysfunction, and in humans, polymorphisms and gain-of-function mutations in this gene have been linked to obesity." (PMID 39033139, 2024). "Almost at the same time, our group discovered in humans a novel low-frequency functional missense in LGR4 (A750T), that has been linked with increased obesity risk and metabolic disorders in a study of Chinese obese patients versus controls." (PMID 30065654, 2018). "The strongest evidence for Wnt/β-catenin pathway module involved in obesity is first from the patients carrying mutations of LGR4, which is a Wnt-FZD-LRP5/6 complex coreceptor." (PMID 30065654, 2018). "The association of LGR4 with human obesity has been demonstrated by a case–control study of early-onset obesity in which four SNPs, located in the encoding and flanking regions of the LGR4 locus, were found to be significantly correlated with body mass index." (PMID 26379625, 2015). "Moreover, a functional low-frequency missense variant of Lgr4 has been associated with an increased risk of obesity." (PMID 34832073, 2021). "Mice homozygous for the Lgr4 mutation, which acts as the receptor for the Wnt agonist R-spondins (Rspos) to enhance canonical Wnt signaling, showed reduced adiposity and resisted obesity." (PMID 34832073, 2021). "Furthermore, a Chinese study that compared obese subjects with control subjects found that a heterogenous variant of c.2248G>A within LGR4 is associated with obesity." (PMID 34707566, 2021). "Intrascapular BAT bilateral sympathectomy eliminated protection from diet-induced obesity in Agrp-Lgr4−/− mice." (PMID 40069508, 2025). "The expression levels of LGR4 must be tightly regulated, as both insufficient and excessive levels can lead to detrimental conditions, such as osteoporosis, delayed puberty, obesity, and cancer." (PMID 40149584, 2025). "Mice with global ablation of LGR4 demonstrate a decrement in adiposity and resistance to dietary and leptin mutant-induced obesity." (PMID 40069508, 2025). "Here, we showed that knockdown of Lgr4 in nestin progenitor or Sp1 mature neurons reduced high fat diet (HFD)-induced obesity by increasing energy expenditure and inhibiting food intake." (PMID 40069508, 2025). "Our study thus suggests that targeting intestinal LGR4 is a potential strategy for the intervention of obesity and liver steatosis." (PMID 38782937, 2024). "LGR4 expression level needs to be tightly controlled: too little or too much of LGR4 can lead to impairments, such as osteoporosis, delayed puberty, obesity, and cancer." (PMID 35707461, 2022). "A recent study reported that RSPO1/LGR4 axis was involved in obesity-related renal fibrosis through promoting Wnt/β-catenin signaling pathway, providing a potential therapeutic target for the obesity-related chronic kidney disease (CKD)." (PMID 35140734, 2021). "Recent reports show that LGR4 homozygous mutant (LGR4m/m) mice display reduced adiposity and are resistant to diet- or leptin-induced obesity." (PMID 30344016, 2019). "Our results demonstrate that ablation of Lgr4 in mice resists dietary and leptin mutant-induced obesity and its metabolic complications, and further prove the crucial role of LGR4 in obesity." (PMID 30065654, 2018).
Obesity (continued). "In line with this strategy, we have previously identified that a gain-of-function variant in LGR4 and rare loss-of-function variants in NPC1 predispose to obesity." (PMID 28988979, 2017). "Recent studies have also revealed a relationship between LGR4 and energy metabolism in areas ranging from food intake and obesity to lipid metabolism." (PMID 26379625, 2015). "Neuronal deficiency of LGR4 improves hypothalamic leptin sensitivity via suppression of β- catenin signaling, which subsequently increases energy expenditure and decreases food intake, thus rendering mice resistant to high fat diet (HFD)-induced obesity." (PMID 40069508, 2025). "Thus, our data indicate knockdown of LGR4 in Agrp specific neurons resistant to HFD induced obesity by increasing energy expenditure and reducing food intake." (PMID 40069508, 2025). "Targeting hypothalamic LGR4 may thus provide a more promising strategy for the intervention of obesity and its related metabolic dysfunction." (PMID 40069508, 2025). "Antagonism of hypothalamic LGR4 may thus provide a novel strategy for the intervention of obesity and its related metabolic dysfunction." (PMID 40069508, 2025). "Our study thus suggests that targeting intestinal LGR4 may provide a potential strategy for the intervention of obesity and liver steatosis." (PMID 38782937, 2024). "This suggests that LGR4 activity promotes fat storage, which may explain the obesity-related LGR4 phenotypes observed in mammals." (PMID 39033139, 2024). "In vitro studies showed that this non-synonymous variant has gained higher biological function than wild-type LGR4, which indicates increased LGR4 activity could promote human obesity." (PMID 30065654, 2018). "Many of the identified CpGs are located in open sea regions, are often close to obesity-related genes such as GPX1 and LGR4 and altogether, are enriched in cancer and oxidative stress pathways." (PMID 36446949, 2022).
osteoporosis (14 papers, 2016 to 2025). A condition of reduced bone mass, with decreased cortical thickness and a decrease in the number and size of the trabeculae of cancellous bone (but normal chemical composition), resulting in increased fracture incidence. "During this time, evidence has continued to show that LGR4 deletions are highly associated with osteoporosis." (PMID 40469438, 2025). "MiR-137 was correlated with an increased risk of fracture in patients with osteoporosis by targeting LGR4/ALP expression." (PMID 35140734, 2021). "Further studies using mouse models are warranted to determine whether LGR4 functions as a pathogenic gene in osteoporosis or high bone mass." (PMID 40149584, 2025). "Deficiency of LGR4 leads to osteoporosis, whereas the up-regulation of LGR4 may help to alleviate the development of traumatic osteoarthritis." (PMID 40469438, 2025). "Interestingly, the injection of a soluble form of the Lgr4 extracellular domain abrogated RANKL-induced bone loss in three mouse models of osteoporosis." (PMID 35052478, 2022). "We not only provided new insight into the mechanism of unloading induced bone loss, but also indicated that Rspo1/Lgr4 could be a potential therapeutic target for treating disuse osteoporosis." (PMID 28272338, 2017). "Interestingly, a mutation in LGR4 encoding gene has been related to an osteoporosis phenotype which can be explained by the new function of LGR4 as a RANKL receptor." (PMID 27279652, 2016). "LGR4 exhibits corresponding functions in bone resorption and bone formation, for which we can consider it as a potential target for the treatment of osteoporosis." (PMID 40469438, 2025). "The soluble extracellular domain of LGR4 (LGR4-ECD) has emerged as a potential new therapeutic for osteoporosis, revealing another promising target for enhancing beta-cell mass in diabetes." (PMID 40612435, 2025). "We found specific osteoporosis-linked SNPs in genes encoding key receptors involved in bone metabolism that are classified into rhodopsin (ADRB2, CNR2, MTNR1B, FSHR, TSHR, LGR4), secretin (CALCR, GIPR), and other T7M (WLS) receptor families." (PMID 39769358, 2024). "The extracellular domain of LGR4 (LGR4-ECD) has emerged as a potential new therapeutic for osteoporosis and cancer." (PMID 35707461, 2022). "They tested the therapeutic potential of LGR4-ECD against osteoporosis, through binding RANKL and thus, preventing its binding to RANK on osteoclasts (see section 6)." (PMID 35707461, 2022). "Whether the normal expression of lgr4 can be restored by gene editing technology to treat osteoporosis is worth studying." (PMID 40469438, 2025). "In studies on osteoporosis, we found that LGR4 can bind to RANKL." (PMID 40469438, 2025). "Furthermore, recent findings indicated that a novel RANKL variant induces the expression of LGR4 via the GSK3-β signaling pathway, thereby suppressing NFATc1 activity and inhibiting osteoporosis." (PMID 40149584, 2025). "In addition, we detected intron variants in MTNR1B, LGR4, and WLS genes that are associated with osteoporosis, increased fracture risk, and low BMD." (PMID 39769358, 2024). "Our previous report showed that LGR4-ECD protein could directly inhibit osteoclast differentiation in 3 murine osteoporosis models." (PMID 34847079, 2022). "No rare human diseases associated with LGR4 have been found, but a rare nonsense variant has been linked to osteoporosis in two different association studies and common variants are associated with heel BMD." (PMID 35052478, 2022). "In addition, a latest finding showed that the novel RANKL variant induced the expression of LGR4 by the GSK3-β signaling, thus suppressing the activity of NFATc1 and inhibiting osteoporosis." (PMID 35140734, 2021). "Rspo1/Lgr4 could be a new potential target for the prevention and treatment of disuse osteoporosis in the future." (PMID 28272338, 2017).
osteoporosis (continued). "LGR4, on the other hand, inhibits osteoclastogenesis upon RANKL binding, thus tightly regulating bone resorption, which when excessive leads to osteoporosis." (PMID 35707461, 2022). "Besides the significance of the membrane-bound LGR4, its soluble form- LGR4-ECD exhibits promising therapeutic potential in osteoporosis and cancer/metastasis progression treatment." (PMID 35707461, 2022). "The fact that LGR4-ECD has an anti-osteoporotic effect indicates its direct interference with RANKL-RANK pathway, which triggers osteoclastogenesis and when excessive, leads to osteoporosis." (PMID 35707461, 2022). "In a previous study, treatment with mutant-type mouse RANKL (mRANKL-MT) in in vitro and in vivo osteoporosis experimental models significantly inhibited the differentiation and production of osteoclasts, which suggested a potential crosstalk between RANKL–RANK and LGR4 signaling." (PMID 33406741, 2021). "Injecting mice with soluble LGR4-ECD, a free protein that binds to ligands but does not activate signaling pathways, can treat osteoporosis." (PMID 40469438, 2025).
prostate carcinoma (12 papers, 2016 to 2024). A carcinoma that arises from epithelial cells of the prostate gland. "However, LGR4 is known as a diagnostic marker in prostate cancer." (PMID 31640282, 2019). "Accordingly, future work to establish if LGR4/5/6 amplification in metastatic prostate cancer promotes Wnt signaling to facilitate advanced prostate cancer progression is needed." (PMID 35204808, 2022). "Some studies have confirmed the direct binding of LGR4 by miR-137 in prostate cancer cells, U-2 and MC3T3 cells." (PMID 36121915, 2022). "In prostate cancer, miR-218 prevents prostate cancer cell proliferation and invasion by inhibition of LGR4." (PMID 33946652, 2021). "Remarkably, LGR4 inhibition confers radiation sensitivity only in AR-positive prostate cancer by regulating the activation of CREB1, a transcription factor that promotes DNA repair." (PMID 33946652, 2021). "It is interesting to note that LGR4 expression can also be targeted by some microRNAs in prostate cancer cells." (PMID 33946652, 2021). "In a xenograft mouse model, LGR4 silencing in prostate cancer cells led to a delay of metastases and reduced expression of EMT markers." (PMID 31083655, 2019). "Ablation of Lgr4 in the prostate cancer cell line DU145 showed that migration, invasion, and EMT-TF expression were decreased, conversely, E-cadherin expression was increased." (PMID 30463358, 2018). "Expression of the leucine-rich repeat-containing G protein-coupled receptor 4 (Lgr4) in human prostate cancer cell lines correlates with invasiveness and metastatic potential of these cells." (PMID 30463358, 2018). "Genes encoding FZD2-5, FZD8, VANGL1, ROR1, RYK, LGR4, LRP5 and 6, and GPC4 were highly expressed in at least three prostate cancer cell lines." (PMID 29717114, 2018). "GPR48/LGR4 is also overexpressed in prostate cancer, concomitant with activation of the PI3K/AKT signaling pathway." (PMID 29383135, 2017). "The expression of LGR4 was elevated after prostate cancer radiotherapy." (PMID 35140734, 2021). "Interestingly, LGR4 inhibition affects tumorigenic capacity and metastasis in vivo in a prostate cancer murine model." (PMID 33946652, 2021). "Moreover, LGR4 was overexpressed in human prostate cancer and correlated with shorter disease-free survival." (PMID 35140734, 2021). "LGR4 plays an important role in prostate cancer progression." (PMID 33946652, 2021). "Higher LGR4 expression correlates with unfavorable prognosis in breast and prostate cancer." (PMID 31083655, 2019). "Indeed, LGR4 is a regulator of radiosensitivity in cancer, e.g., in prostate cancer cells, and the RSPO1–LGR4 axis could be an important protection factor against the radiation effects of mesenchymal bone stem cells." (PMID 39769183, 2024). "LGR4 may also facilitate the growth of prostate cancer via the PI3K/Akt/mTOR signaling." (PMID 35140734, 2021). "Thus, Lgr4 plays an essential role in prostate cancer EMT and metastasis." (PMID 30463358, 2018). "LGR4 inhibition decreases proliferation, invasion, migration, EMT processes, metastasis, and increases apoptosis of prostate cancer cells." (PMID 33946652, 2021). "A recent study showed that radiation treatment enhances the expression of both LGR4 and its ligands in AR-positive and negative prostate cancer cells." (PMID 33946652, 2021). "Recent evidence has shown that LGR4 over-expression increased the expression level of the androgen receptor, a transcription factor that controls PSA transcription and plays essential roles in prostate cancer progression." (PMID 33946652, 2021). "Furthermore, hypoxia exposure downregulated the expression of miR-137, which targeted LGR4 and prevent the migration and EMT of prostate cancer by inhibiting EGFR/ERK signaling." (PMID 35140734, 2021). "MiR-137 also inhibits prostate cancer cell migration and epithelial-mesenchymal transition (EMT) by negatively regulating the epidermal growth factor receptor/extracellular signal-regulated kinase (EGFR/ERK) through LGR4 targeting." (PMID 33946652, 2021).
prostate carcinoma (continued). "No direct association between LGR4 and CRC has yet been reported; however, increased LGR4 mRNA levels were observed in prostatic cancer." (PMID 29316729, 2018).